MAVS (mitochondrial antiviral signaling protein)
Diseases named in the same sentence as MAVS in open-access papers (continued):
Sharing a sentence is not in itself a finding about the gene and the disease.
viral infection (continued). "Compared to MAVS-ΔN141, these chimeric mutants MAVS-ΔN141-(Bcl-xL-TM) and MAVS-ΔN141-(VAMP-2-TM) lost their inhibitory effects on IFN production and MAVS aggregation upon virus infection, though they contain active regions for interaction with downstream effectors." (PMID 28607490, 2017). "Chickens lack RIG-I (retinoic acid-inducible gene I), but the function of sensing viral infections can be performed by LGP2 and MDA5, which can interact with MAVS (mitochondrial antiviral signaling protein) or STING (stimulator of IFN genes) to stimulate the expression of IFNs." (PMID 29178824, 2017). "In MAVS-deficient cells, however, neither NEMO-WT nor NEMO-Mut was found to bind ubiquitin chains after viral infection, indicating that MAVS activation initiated ubiquitin chain synthesis and subsequent NEMO binding." (PMID 29125880, 2017). "Remarkably, MAVS mutants, but not wild type MAVS, form prion-like aggregates in the absence of virus infection." (PMID 28607490, 2017). "Overexpression of MAVS increased the expression of IFN-α/β and ISGs through activation of IRF3/7 and NF-κB; moreover, the induction of type I IFNs and antiviral immune response to viral infection were impaired after knockdown of MAVS." (PMID 27708647, 2016). "Recently, the adaptor protein endoplasmic reticulum IFN stimulator (STING, also known as MITA/ERIS), along with MAVS and TBK1, were identified for their contribution to STAT6 activation during viral infection with Semiliki Forest virus and herpes simplex virus 1 (HSV-1)." (PMID 27143388, 2016). "Cytosolic viral RNA recognized by RLRs can activate MAVS and recruit various signaling molecules to transduce the downstream pathways, such as type I interferon (IFN) production and cell death induction, two major cellular events controlling viral infection." (PMID 26717518, 2015). "Thus, MFNs interact with MAVS and modulate RLR signaling, but the detailed involvement of these two MFNs in viral infection is largely unclear." (PMID 26717518, 2015). "Given the importance of the RIG-I/MAVS pathway, it is critical to keep them in the quiescent state in the absence of virus, but trigger their activation rapidly on viral infection." (PMID 26183716, 2015). "NSP1 was found to co-immunoprecipitated with MAVS both during viral infection and overexpression suggesting an interaction in absence of other viral protein." (PMID 24643253, 2014). "Since MAVS is anchored on the mitochondrial outer membrane, we reasoned that MKK7 could dynamically be recruited onto mitochondria upon virus infection." (PMID 24651600, 2014). "The NSP1 mutant RV strain A5-16 was used for virus infection, since it does not degrade cellular MAVS." (PMID 24643253, 2014). "Unlike wild-type MAVS, which activated IRF3 and formed SDS-resistant aggregates following viral infection, MAVS containing point mutations in the CARD domain failed to activate IRF3 or form aggregates." (PMID 23951545, 2013). "Alternatively, in MAVS−/− and IRF3−/−IRF7−/− cells, minute, steady state amounts of IFNs could still be produced and be sufficient to induce ISGs in a context of viral infection." (PMID 24278020, 2013). "However, TRAF3 was demonstrated to link the mitochondrial membrane-bound protein MAVS to the activation of TBK1, which is required for IRF3/7 phosphorylation and type I IFN induction in response to viral infection." (PMID 22792062, 2012). "The RIG-I/MDA-5/MAVS pathway plays an essential role for initiating cellular signals leading to the activation of transcription factors and subsequent induction of type I IFN in the course of viral infections." (PMID 18516301, 2008). "Moreover, glucose restriction may reduce lactate production and relax lactate-mediated inhibition of MAVS, IRF3, and NF-κB signaling, enhancing the IFN-I response and impairing viral infection." (PMID 40391966, 2025).
viral infection (continued). "Additionally, lactate binds to mitochondrial antiviral-signaling protein (MAVS), inhibiting retinoic acid-inducible gene I-like receptor (RLR)-mediated type I interferon production in macrophages, thereby providing resistance to viral infections in vivo." (PMID 40421024, 2025). "In addition, MAVS knockdown failed to attenuate pitavastatin-induced RIG-I expression in the absence of viral infection (Fig. EV2C), implying that geranylgeranylation of MAVS is not involved in statin-induced RIG-I expression." (PMID 39668245, 2025). "Interestingly, the overexpression of VP3 can promote virus replication and reverse the inhibitory effect of MAVS on the virus, suggesting that VP3 plays a critical role in sustaining viral infection and may function similarly in related viruses." (PMID 40042308, 2025). "However, our study revealed that statin treatment can elevate the expression of noncanonical type I IFNs even in the absence of viral infection, a condition in which MAVS is not activated." (PMID 39668245, 2025). "It is reported that SERINC5 interacts with MAVS and enhances the formation of MAVS polymers at mitochondria after virus infection, which recruits TRAF6, are essential for NF-κB signaling (NF-κB is the transcription for IFN in response to viral infections and immune responses)." (PMID 39902183, 2024). "We also tested whether MAVS and IRF3 localize to SGs in response to viral infection." (PMID 38295168, 2024). "It was reported that viral infection could induce the formation of very large MAVS aggregates, which potently activate IRF3 in the cytosol; thus, we investigated whether succinate could reduce the aggregation levels of MAVS induced by VSV infection." (PMID 35309330, 2022). "We can thus not say whether the engineered mvRNAs affect the MAVS signaling pathway in the same way during viral infection as in our RNP reconstitution experiments." (PMID 36083899, 2022). "The proteases responsible for MAVS degradation are most likely derived from host cells rather than viruses, as MAVS can be restored in ATP13A1‐deficient cells following protease inhibitors treatment without virus infection." (PMID 36216581, 2022). "The 70 kDa MAVS was downregulated, while the expression level of a smaller (45–50 kDa) band reactive with caMAVS antibodies was upregulated at 48 h with/without virus infection for reasons unknown." (PMID 33807534, 2021). "A cell detects viral infection by pattern recognition receptors, which signal through one of three independent mechanisms–STING (Stimulator Of Interferon Response cGAMP Interactor), MAVS (Mitochondrial Antiviral Signaling Protein) or some members of the TLR (Toll-Like-Receptor) family." (PMID 34437657, 2021). "Interestingly, this phenomenon occurs upon viral infection in the presence of RIG-I; thus, recruitment of RIG-I may be required for TRIM31-mediated MAVS aggregation upon viral infection." (PMID 34782737, 2021). "Viral infection experiments demonstrated that the IAV WT virus, but not NS1 E152A/153A virus, effectively suppressed the K63-linked ubiquitination of TRAF3 induced by RIG-I-CARD and MAVS respectively." (PMID 34610835, 2021). "Our group further discovered that in the absence of viral infection, endogenous MAVS produced by internal ORF-deleted transcripts could spontaneously aggregate and activate the IFN signaling pathway." (PMID 34566944, 2021). "These DUBs mainly regulate the polyubiquitination levels of RIG-I, STING, MAVS, TRAFs, and TBK1, which function at different levels of this pathway, and this finding implies the physiological importance of these master proteins in innate immunity during viral infections." (PMID 34707613, 2021). "However, viral infection did not lead to disappearance of RNF115 from the mitochondrial fractions or mitotracker, suggesting that viral infection-resulted impairment of RNF115 and MAVS association is not due to disassociation of RNF115 from mitochondria." (PMID 33139700, 2020).
viral infection (continued). "However, other studies reported that MAVS is required for NLRP3 inflammasome activation by viral infections, but not by non-viral NLRP3 stimuli." (PMID 31284572, 2019). "Indeed, both viruses are sensed by the RLRs because the absence of the adaptor MAVS completely abrogated the production of IFNβ following viral infection." (PMID 31024004, 2019). "Upon viral infection, the recognition and binding of exogenous RNA structures leads to a conformational switch of RIG-I, which releases the auto-repressed CARDs and recruits its downstream adaptor mitochondrial antiviral-signaling protein (MAVS) at mitochondria and peroxisomes." (PMID 30241345, 2018). "In contrast, MAVS-ΔTM could not inhibit the IFN production on virus infection, suggesting that TM domain is indispensable for the inhibitory effect observed." (PMID 28607490, 2017). "Consistently, MAVS could not form aggregates on virus infection in the absence of both Ube2D3 and Ube2N." (PMID 28469175, 2017). "Strikingly, Bcl-xL-TM, VAMP-2-TM or Pex13-TM could not inhibit MAVS activity in inducing IFN production following virus infection, nor was MAVS aggregation affected." (PMID 28607490, 2017). "However, we observed the reduced expression of both RIG-I and MAVS during WT PRRSV infection, suggesting nsp11 may preserve the same function during viral infection." (PMID 27997564, 2016). "Pigeon RIG-I dispersoid distributed throughout the cytoplasm of DF-1 cells and could only partly overlay with chicken MAVS, not human MAVS, upon virus infection, indicating that pigeon RIG-I only function in chicken cells but not in human cells." (PMID 26205406, 2015). "Full-length MAVS could only induce ISG54 expression in response to Sendai virus infection, while MAVS (Δaa-141–300) induced ISG54 expression regardless of virus infection." (PMID 26183716, 2015). "Following virus infection, activation of the RIG/MAVS pathway leads to TBK1 activation (presumably through phosphorylation by an upstream unknown kinase and ubiquitination by the E3 ligases MIB1/2 or Ndrp1) and to the disruption of its interaction with Optn and CYLD." (PMID 25923723, 2015). "Our model that MAVS signals through multiple TRAF proteins is further supported by mutagenesis experiments which showed that mutations of both TRAF2/5 and TRAF6 binding sites of MAVS, but not each alone, abolished IRF3 and IKK activation by virus infection." (PMID 23951545, 2013). "Furthermore, mutations of the binding sites for TRAF2, TRAF5, and TRAF6 on MAVS abolished the ability of MAVS to activate downstream signaling after virus infection, without affecting its ability to form prion-like polymers." (PMID 23951545, 2013). "In addition to K63-ubiquitination at MAVS K500, MAVS can link K48-polyubiquitin chains following virus infection and is the target for proteasomal degradation by the E3 ligase RNF125, suggesting that MAVS may undergo multiple ubiquitination events." (PMID 22844514, 2012). "As expected from previous studies, over-expression of the MAVS protein strongly induced the expression of endogenous IFNβ in control MEFs, even in the absence of viral infection, and SeV-induced IFNβ expression was enhanced in cells in which MAVS was over-expressed." (PMID 21677781, 2011). "Moreover, consistent with previous reports showing the recruitment of TRAF3 to MAVS as an important process leading to downstream signaling, the silencing of TFG also blunted the activating transautophosphorylation of TBK1 on Ser172 (p-TBK1 Ser172) normally observed upon viral infection." (PMID 33411856, 2021). "However, to date, no study has investigated whether MAVS expression is regulated by aMPV/C infection and if so, how it is regulated during viral infection." (PMID 34696420, 2021). "Notably, TRIM31-mediated MAVS aggregation does not occur under RIG-I deficient or non-viral infection conditions, thus it can be considered that RIG-I engagement is required for TRIM31-mediated MAVS aggregation after viral infection." (PMID 32536927, 2020).
viral infection (continued). "Nonetheless, an intriguing possibility is that the regulation of B cell responses by MAVS/type I IFN signaling in CD11c+ DCs could be part of a feedback loop to avoid over activation of innate and adaptive immune responses and control pathological inflammation during viral infection." (PMID 31242236, 2019). "Given that MAVS is a mitochondrial protein and Smurf1 can regulate MAVS/TRAF3/TRAF6 proteins during RNA virus infection, we speculate that upregulated Smurf1 proteins by viral infection could be able to localize to the mitochondria to interact with the MAVS/TRAF3/TRAF6 signalosome." (PMID 29734366, 2018). "Finally, after its induced synthesis following viral infection, poly(RC) binding protein 2 (PCBP2) negatively regulates the RIG-I/MAVS signaling pathway by interacting with MAVS and recruiting E3 ligase atrophin-1-interacting protein 4 (AIP4) for MAVS degradation by the proteasome." (PMID 29642643, 2018). "Indeed, MAVS could not form prion-like aggregates under sh-Ube2N treatment in response to virus infection." (PMID 28469175, 2017). "Although they showed no mechanisms of how the SNPs in MAVS influence the clinical symptoms of RVF, their reuslts supported our hypothesis in the present study: that is, that the SNPs in MAVS are functionally associated with susceptibility to viral infection." (PMID 26954674, 2016). "In addition, sumoylated PCBP2 neither affect the interaction between MAVS and PCBP2, nor the association of RIG-I or MDA5.These data indicate that the sumoylated PCBP2 leads to its nuclear export during the progress of virus infection." (PMID 26348439, 2015). "Our data showed that pCARDs co-localized with human MAVS and itself as dot-like structures in 293T cells with or without infection, implying that pCARDs could directly trigger the downstream signaling without virus infection." (PMID 26205406, 2015). "The pRIG-I-EGFP dispersoid distributed throughout the cytoplasm of DF-1 and 293T cells, however, pCARDs-EGFP typically localized as dot-like structures in both the cytoplasm and nucleus, implying that pCARDs may directly interact with MAVS and recruit downstream proteins without any virus infection." (PMID 26205406, 2015). "Despite the lack of a MAVS ortholog in C. elegans, an analogous response is occurring, as DRH-1 translocates to the mitochondria after viral infection, and mitochondria still serve as the focal point for initiating antiviral response." (PMID 41039133, 2025). "The role of MAVS downstream of BCR stimulation was recognized in absence of IFN, indicative of a path for MAVS activation that is independent of viral infection." (PMID 37610299, 2023). "Moreover, SZ19-ΔF2 virus infection specifically enhanced the K27-linked, but not K48- or K63-linked endogenous ubiquitination of MAVS, in contrast, knockdown of PB1 inhibited the SZ19-ΔF2-induced K27-linked, but not K48- or K63-linked endogenous ubiquitination of MAVS." (PMID 33577621, 2021). "It is not surprising that the expression of MAVS is regulated to ensure that RLR-mediated signaling cascades are not activated rapidly upon stimulation; indeed, its function at this stage of viral infection is to prevent rapid viral replication." (PMID 34782737, 2021). "The second model suggests that MAVS recruits TBK1 through TBK1 binding proteins NAP1 or SINTBAD, however knock-down of these two proteins did not impair type I-IFN production after viral infection." (PMID 29125880, 2017). "Under the same experimental condition, we found that RIG-I (left), but not MAVS (right), was in the immune complexes with GLTSCR2 regardless of viral infection." (PMID 27824081, 2016). "Taken together, we observed efficient MAVS-dependent activation of the type I and III IFN response upon virus infection, independent of the subcellular localization of MAVS." (PMID 26588843, 2015).
viral infection (continued). "Accordingly, the combined absence of IFNAR and MAVS resulted in enhanced infection without early “cytokine storm”, with DKO mice succumbing to infection days later likely due to massive virus infection in the central nervous system." (PMID 24743949, 2014). "NF-κB, which is activated by MAVS and can contribute to IFN I-signalling did not appear to play a role in the induction of Noxa as no NF-κB activity was induced by viral infection." (PMID 21698224, 2011). "For example, mice lacking MAVS were severely compromised in innate immune defense against VSV infection, leading to an elevated peak viral load and prolonged acute viral infection." (PMID 20686657, 2010). "In addition to viral infection, we found that activation of RIG‐I‐like (RLR) signaling (RIG‐I and MAVS) rather than IFN signaling contributed to the transactivation of NEURL3." (PMID 35792897, 2022). "Upon viral infection, PCBP2 expression is induced and similarly bridges AIP4 to target MAVS-K371/K420 for degradation at later stages of infection, serving as a possible negative feedback mechanism to terminate MAVS signaling." (PMID 35795661, 2022). "In addition to processing host factors such as RIG-I and MAVS, Nsp5 processes several nonstructural proteins of SARS-CoV-2, thus playing essential roles in key processes of viral infection, such as genome replication." (PMID 34544279, 2021). "However, our LC-MS/MS analysis did not detect any peptide derived from MAVS, a mitochondrial protein that is known to bind to TRAF3 upon viral infection." (PMID 34745083, 2021). "Interestingly, we found that expression of RIG-I impaired RNF115–MAVS but not RNF115–MAVS–TM(VAMP-2) associations, indicating that RIG-I competitively engages MAVS against RNF115 on the mitochondria which might be responsible for the disassociation of RNF115 from MAVS after viral infections." (PMID 33139700, 2020). "Furthermore, PKR activation by virus was impaired in cells lacking MDA5, and studies involving artificial PKR activation in the absence of virus infection demonstrated IRF3 phosphorylation and IFN expression in a MAVS-dependent, but MDA5-independent fashion." (PMID 26939124, 2016). "Furthermore, the same group recently reported that upon viral infection pexMAVS induces IFN-λ1, but not IFN-β in Huh7 cells after knockdown of endogenous MAVS expression." (PMID 26588843, 2015). "However, compared with the virus-infected group, the 6.25 μg/mL naringenin group, to which Cyclo (Phe-Pro) was added along with the virus infection, did not up-regulate the protein expression of RIG-I and MAVS, but instead significantly inhibited the protein expression of RIG-I and MAVS." (PMID 38005850, 2023). "Hence, these results indicate that in mammalian cells TRIM25 is recruited into stress granules upon stimulation of the innate immune response ether by transfection-based plasmid overexpression or virus infection, where it interacts with RIG-I, but not with MAVS." (PMID 36519174, 2022). "In addition to inducing MAVS activation independent of dsRNA receptor signaling, oxidative stress may also enhance the expression of MDA5 in the absence of viral infection." (PMID 31796819, 2019).